IL13 (interleukin 13)
Diseases named in the same sentence as IL13 in open-access papers (continued):
Sharing a sentence is not in itself a finding about the gene and the disease.
HCMV infection (2 papers, 2017 to 2020). "In particular, HCMV infection led mainly to the over-expression of CCL2, CCL3, CCL11, CXCR4, IL-1β, IL13, MMP1, MMP3, MMP9 and MMP13, SERPINA1, TNFα, and BMP7, and the gradual and constant downregulation of IL13RA2 (up to almost 800-fold at 14 days p.i.)." (PMID 32899126, 2020).
head and neck squamous cell carcinoma (2 papers, 2020 to 2022). A squamous cell carcinoma that arises from any of the following anatomic sites: lip and oral cavity, nasal cavity, paranasal sinuses, pharynx, larynx, and salivary glands. "IL13-PE is highly cytotoxic to human solid tumor cell lines, including those derived from RCC, GBM, and head and neck squamous cell carcinoma (HNSCC)." (PMID 35464460, 2022).
hematoma (2 papers, 2014 to 2023). A hematoma is a collection of blood from a vascular structure into an extravascular space. "Exploratory factor analysis indicated two major underlying immunological processes expressed by the cytokines in both blood and hematoma fluid, but with a different pattern and particularly regarding the cytokines IL-13, IL-6, IL-4 and TNF-α." (PMID 24587250, 2014). "Results from the two exploratory factor analysis models indicated a different underlying cytokine pattern in venous blood compared with hematoma fluid samples, which seemed especially so for the pro-inflammatory cytokines IL-6 and TNF-α and the anti-inflammatory cytokines IL-4 and IL-13." (PMID 24587250, 2014). "In the earlier prospective cohort study of these two researchers on 57 patients, an association between increased hematoma fluid (but not serum) of a panel of biomarkers considered an anti-inflammatory index (IL-4, IL-5, IL-10, IL-13, IL-1 RA) and a reduced risk of recurrence was indicated." (PMID 37510193, 2023). "In particular, the cytokines IL-13, IL-6, IL-4 and TNF- α exhibited differences in loadings between an exploratory factor analysis from blood and hematoma samples." (PMID 24587250, 2014). "The IL-6 and CXCL8 in blood samples and CCL2, IL-5 and IL-13 in hematoma samples did not have significant standardized loadings, and were therefore excluded from the statistical models." (PMID 24587250, 2014). "In the same study, a positive association between hematoma fluid CCL5 (also termed regulated on activation, normal T-cell expressed and secreted, RANTES) levels and recurrence as well as a negative association between IL-5, IL-13, IFN-γ and CXCL10 levels and recurrence was also indicated." (PMID 37510193, 2023). "Since the cytokines IL-13, IL-6, IL-4 and TNF-α in particular displayed a different loading pattern in blood compared to hematoma fluid samples, they could play a different role in the local inflammatory response in the hematoma compared with the systemic response assessed in blood samples." (PMID 24587250, 2014).
HIV-1 infection (2 papers, 2014 to 2019). The type species of lentivirus and the etiologic agent of acquired immunodeficiency syndrome (AIDS). "Individual cytokines (IL-10 and IL-13) correlated with a decreased risk of HIV-1 infection." (PMID 24932411, 2014). "In line with our results, it has been demonstrated that IL-13 inhibited HIV production in primary blood-derived human macrophages in vitro and that IL-13 and IFNγ secretion by activated T cells in HIV-1 infection was associated with viral suppression and a lack of disease progression." (PMID 31498845, 2019).
Huntington disease (2 papers, 2010 to 2026). Huntington disease (HD) is a rare neurodegenerative disorder of the central nervous system characterized by unwanted choreatic movements, behavioral and psychiatric disturbances and dementia. "To evaluate whether cytokines are altered in peripheral blood of rats transgenic for the human Huntington ́s disease mutation we investigated serum levels of GRO/KC, IL-1β, IL-13 and TNF-α at a symptomatic stage at 12 months of age." (PMID 20981129, 2010).
Hyperinsulinemia (2 papers, 2013 to 2018). An increased concentration of insulin in the blood. "Compared to a reference bottlenose dolphin without metabolic perturbations, the current study identified activated cytokine gene expression, including TGF-β, TNF-α, IFN-γ, IL-18, IL-13, IL-10, and IL-4 in the liver or spleen of a geriatric bottlenose dolphin with hyperinsulinemia." (PMID 24101915, 2013). "Due to the pro-inflammatory nature of hyperinsulinemia, it is not surprising that corresponding anti-inflammatory cytokines, IL-4, IL-10, IL-13, and TGF-β, would also be upregulated in an effort to control the inflammation." (PMID 24101915, 2013).
hyperthyroidism (2 papers, 2024 to 2025). Overactivity of the thyroid gland resulting in overproduction of thyroid hormone and increased metabolic rate. "The presence of interleukin-13 (IL-13) and macrophage migration inhibitory factor (MIF) are causally associated with hyperthyroidism (OR = 1.046, 95% CI: 1.008–1.086, p = 0.019; OR = 1.052, 95% CI: 1.007–1.099, p = 0.022, respectively)." (PMID 38872961, 2024). "Analysis of serum samples showed no notable changes in IL-13 concentrations in treatment-naïve GD patients presenting with hyperthyroidism." (PMID 40895623, 2025).
ichthyoses (2 papers, 2022 to 2025). "g., anti-TNF-α, anti-IL-17, and anti-IL-4/IL-13 antibodies) have been reported as useful treatments for several types of inherited ichthyoses." (PMID 36332686, 2022).
irritable bowel syndrome (2 papers, 2018 to 2023). Irritable bowel syndrome (IBS) is a chronic functional condition of the lower gastrointestinal (GI) tract characterized by abdominal pain or discomfort and disordered bowel habit (diarrhea, constipation, or fluctuation between the two). "Veillonellaceae has been associated with exacerbating inflammation (IL-13, IL-6) and higher prevalence in patients with hepatic encephalopathy and irritable bowel syndrome patients." (PMID 37763331, 2023).
Kaposi's sarcoma (2 papers, 2010 to 2020). A malignant neoplasm characterized by a vascular proliferation which usually contains blunt endothelial cells. "In the IRIS patient that presented with Kaposi's sarcoma, increases in IL-6, IL-10, IL-12, IL-13 and IFN-γ expression were shown." (PMID 20929543, 2010).
leukocytosis (2 papers, 2017 to 2021). "Accordingly, HDM exposure caused increased leukocytosis in the bone marrow, blood and BALF, mainly due to eosinophils, and elevated serum IgE and IL13 levels, as we reported." (PMID 34440118, 2021).
lichen planus (2 papers, 2025). A chronic, recurrent, pruritic inflammatory disorder of unknown etiology that affects the skin and mucus membranes. "Although the exact mechanism remains unclear, it has been proposed that dupilumab's inhibition of IL-4 and IL-13 may indirectly downregulate IL-6-driven Th2 responses, which are elevated in patients with lichen planus and may contribute to disease persistence." (PMID 40718341, 2025).
metastatic cancer (2 papers, 2020 to 2024). A carcinoma which has spread from the original site of growth to another anatomic site. "In this study, we measured saliva and serum concentrations of TGF-β and IL-13 in cachectic and non-cachectic patients with metastatic cancer and healthy controls." (PMID 39272892, 2024).
myelofibrosis (2 papers, 2024). A partial or complete replacement of the bone marrow stroma by fibrous tissue. "Subsequent investigations have revealed that IL-13 can instigate the expansion and growth of mutant MKs in mice with myelofibrosis models." (PMID 38256942, 2024). "MKs from mice with myelofibrosis models exhibit high expression levels of IL-13Rα1 and IL-4Rα, along with increased expression of IL-13 in bone marrow." (PMID 38256942, 2024).
myeloid leukemia (2 papers, 2016 to 2019). A clonal proliferation of myeloid cells and their precursors in the bone marrow, peripheral blood, and spleen. "Employing a humanized mouse model of myeloid leukemia, blockade of PGD2, IL-13, or NKp30 reversed ILC2-driven immunosuppression and increased the survival of leukemic mice." (PMID 31574995, 2019). "The pathways and genes that significantly changed were classified as follows: cancer pathways (EPAS1, CCND1, FGF13), myeloid leukemia pathways (ZBTB16, KIT, IL13), hematopoietic cell lineage pathways (EPOR, GYPA, CD36) and so on." (PMID 27516205, 2016).
Nasal congestion (2 papers, 2014 to 2025). Reduced ability to pass air through the nasal cavity often leading to mouth breathing. "Elevated WBC may also imply increased levels of cytokines like IL-4, IL-5, and IL-13, resulting in more severe nasal obstruction, rhinorrhea, and loss of smell." (PMID 41473511, 2025).
oral cancer (2 papers, 2020 to 2023). "Previous studies showed associations of increased risk for oral cancer with TNF-β polymorphisms genes and increased expression of salivary IL-4 and IL-13." (PMID 31973090, 2020).
pertussis (2 papers, 2013 to 2018). A contagious bacterial respiratory infection caused by Bordetella pertussis. "We plotted the epitope-specific IFNγ/IL-13 responsiveness of individual pertussis patients (with an epitope proliferative response of S.I. ≥2) against time elapsed since diagnosis grouped as Prn peptide responses or grouped as Ptx peptide responses." (PMID 24391789, 2013). "Pertussis-specific IFN-γ production and FHA-specific IL-13 production decreased significantly between 2 weeks and 1 year post-booster." (PMID 29670634, 2018).
pneumococcal pneumonia (2 papers, 2011 to 2017). A febrile disease caused by STREPTOCOCCUS PNEUMONIAE. "Similar to our observations in pneumococcal pneumonia, we discovered an augmented early inflammatory response to LPS and an improved clearance of S. aureus associated with a reduced disease-associated temperature drop in Il13−/− animals." (PMID 28228256, 2017).
Pneumocystis infection (2 papers, 2019 to 2023). "In addition, as shown in a previous study, Pneumocystis infection can induce both Th2 and Th17 responses, stimulate the secretion of IL-13 and IL-17A, and further facilitate the formation of inducible bronchus associated lymphoid tissue (iBALT) in a Cxcl13-dependent manner." (PMID 37359523, 2023). "Induction of the CLCA1 pathway with increased mucins has been shown to correlate with Pneumocystis infection in humans and in animal models and is strongly related to IL-13 driven mucus cell metaplasia, STAT6 activation and MUC5AC and MUC5B expression in the airways." (PMID 31333624, 2019).
pollen allergy (2 papers, 2020 to 2024). "In an in vitro model of birch pollen allergy that involved birch pollen stimulation of human cord blood cells, downregulation of Th2 responses was observed with a reduction in IL-13 following LPS co-administration." (PMID 33281825, 2020).
prediabetes (2 papers, 2021 to 2024). "Similar analysis in Indians showed significantly higher levels of inflammatory biomarkers like high-sensitive C-reactive protein (hsCRP), IL1β, IL13, IL17A, IL6, TNFα, and IAP in individuals with prediabetes compared to normoglycemic individuals." (PMID 33658065, 2021).
prostate tumours (2 papers, 2018 to 2020). "IL-13 can induce progression of prostate tumours and enhance M2 phenotype polarization of macrophages." (PMID 29587679, 2018).
rhinosinusitis (2 papers, 2012 to 2025). "IL-13 polymorphisms at −1510A > C and 1055C > T are associated with the development of rhinosinusitis in AERD patients." (PMID 21837245, 2012).
RSV bronchiolitis (2 papers, 2019 to 2021). "Furthermore, there is a genetic association between a haplotype at the IL-13-IL-4 gene locus and increased IL-13 production with a correlation in elevated risk of RSV bronchiolitis in childhood." (PMID 30759882, 2019). "The serum level of IL-3, IL-4, IL-10, and IL-13, which originate from Th2 cytokine, were higher in children with RSV bronchiolitis secondary wheezing, and IL-3 can be used as a predictor of recurrent wheezing." (PMID 33691633, 2021).
Schistosoma haematobium infection (2 papers, 2012 to 2021). "Two functional polymorphisms in IL13, rs1800925 (or c.1-1111C>T) and rs20541 (or R130Q) were previously found to be associated with Schistosoma hematobium infection intensity." (PMID 22574126, 2012). "In this study, the relationships between different interleukin gene polymorphisms (IL-13-591A/G, IL-13-1055C/T, IL-13-1258A/G) and Schistosoma haematobium infection levels were evaluated; as well as the host plasma antibodies and cytokine profiles associated with schistosomiasis infection." (PMID 34185775, 2021).
septic shock (2 papers, 2013 to 2023). Shock caused by infection; frequently caused by gram negative bacteria, although some cases have been caused by other bacteria, viruses, fungi, and protozoa; characterized by fever, chills, tachycardia, tachypnea, and hypotension. "Less studied in septic shock are the TH2 cytokines IL4, IL5, IL9 and IL13." (PMID 24244449, 2013).
sialadenitis (2 papers, 2022 to 2024). Sialadenitis is an infection of the salivary glands. "Higher IL-4 and IL-13 levels are identified in the submandibular glands (SMGs) of patients with lgG4-related sialadenitis, which induces salivary gland epithelial cell senescence through ROS/p38 MAPK-p16INK4A pathway or damaging mitochondrial functions." (PMID 38714918, 2024).
sickle cell disease (2 papers, 2013 to 2022). Sickle cell anemias are chronic hemolytic diseases that may induce three types of acute accidents: severe anemia, severe bacterial infections, and ischemic vasoocclusive accidents (VOA) caused by sickle-shaped red blood cells obstructing small blood vessels and capillaries. "The levels of the Th2 type cytokines IL-4, IL-10 and IL-13 are relatively enhanced whereas IFN-γ responses are compromised in thalassemia, sickle cell disease (SCD) and autoimmune hemolytic anemia." (PMID 23358441, 2013).
Strongyloides infection (2 papers, 2017 to 2019). "However, higher values of conventional Th2 cells (IL-4+, IL-13+ or IL-5+) correlated with increased Th2/1 hybrid cell frequencies co-expressing IFN-γ and the respective Th2 cytokines (p < 0.0001) irrespective of the Strongyloides infection status." (PMID 28676845, 2017).
synovitis (2 papers, 2005 to 2024). Inflammation of a synovial membrane. "This study demonstrates that IL-13 stimulation induces periostin production in hFLS, suggesting that IL-13 plays an important role in synovitis associated with KOA." (PMID 38711706, 2024). "Firstly, it remains unclear whether 20 ng/mL of IL-13 is sufficient to trigger synovitis in the articular joint." (PMID 38711706, 2024). "Synovitis, characterized by inflammation in the synovial tissue, plays a crucial role in perpetuating the disease by triggering a cascade of catabolic and proinflammatory mediators, including cytokines, such as interleukin (IL)-1 beta, tumor necrosis factor-alpha, and IL-13." (PMID 38711706, 2024). "Early RA synovial fluid was characterized by significantly elevated levels of T cell related cytokines (IL-2, IL-4, IL-13 and IL-17) and stromal cell and macrophage related cytokines (EGF, bFGF, IL-1 and IL-15) when compared with synovial fluid from patients with other early synovitis." (PMID 15987480, 2005).
toxoplasmosis (2 papers, 2008 to 2020). A parasitic disease contracted by the ingestion or fetal transmission of toxoplasma gondii. "The presence of the same pathology in mice without NRAMP, IL-4, IL-6, or IL-13, each important in immunity to toxoplasmosis, indicates that none of these genes or cytokines are necessary or sufficient to cause this histopathology." (PMID 18947414, 2008).
trachoma (2 papers, 2008 to 2024). "Additional cytokines (Th1, IL-12p40 [r = −0.212, P<0.01], and Th2, IL-4 and IL-13 [r = −0.165 and −0.189, respectively, P<0.05 for both]) were negatively associated with chronic scarring trachoma, suggesting a protective role." (PMID 18628987, 2008). "Studies conducted on human cohorts at different stages of trachoma revealed an association between chronic trachoma and the local presence (in mucosal sponges) of IL-1RA (an antagonist of the pro-inflammatory IL-1), as well as IL-4 and IL-13 (associated with Th2 response)." (PMID 39093884, 2024).
vasculitis (2 papers, 2013 to 2025). "Serum concentrations of BAFF, APRIL, and other cytokines, including IL-4, IL-6, IL-10, and IL-13, can be implicated in the differentiation of B-cell lineages, while significant increases in BAFF, APRIL, IL-4, and IL-6 were observed in patients with ANCA-vasculitis." (PMID 40430184, 2025). "At 4 weeks, the degree of vasculitis, as indicated by the total area of inflammation, correlated with TNF-α and IL-13 levels in each animal of all groups (r = 0.78, P < 0.0001; r = 0.60, P = 0.0003, resp)." (PMID 23606968, 2013).
Wilson disease (2 papers, 2024). A very rare inherited multisystemic disease presenting non-specific neurological, hepatic, psychiatric or osseo-muscular manifestations due to excessive copper deposition in the body. "Compared with controls, in patients with Wilson disease, there was a significant increase of plasma of T helper (Th) 1 cells (IL-2, TNF-α, and TNF-β), Th2 cells (IL-5, IL-10, and IL-13), and Th17 (IL-23) (p < 0.05)." (PMID 38731973, 2024). "Compared with controls, in patients with Wilson disease, there was a significant increase in plasma of T helper (Th) 1 cells (IL-2, TNF-α, and TNF-β), Th2 cells (IL-5, IL-10, and IL-13), and Th17 (IL-23) (p < 0.05)." (PMID 38928368, 2024).
Achilles tendinitis (1 paper, 2018). "In order to investigate the in vivo anti-inflammatory effects of SIM/PMSs on collagenase-induced Achilles tendinitis models, we monitored the mRNA levels of both pro-inflammatory cytokines (MMP-3, COX-2, IL-6, TNF-α, and MMP-13) and anti-inflammatory cytokines (IL-4, IL-10, and IL-13)." (PMID 29534523, 2018).
acute cystitis (1 paper, 2024). An acute infection of the bladder. "This research provides rationale for future studies to further validate urinary IL-8, PGE2, and IL-13 as immune diagnostic biomarkers of UTI and PGE2 as a rUTI prognostic biomarker in larger and more diverse cohorts including those with ASB and acute cystitis." (PMID 38331474, 2024).
acute myeloid leukemia (1 paper, 2023). Acute myeloid leukemia (AML) is a group of neoplasms arising from precursor cells committed to the myeloid cell-line differentiation. "In acute myeloid leukemia (AML), there is a significant enrichment of ILC1s in peripheral blood compared to healthy controls and a significant reduction in the production of IFN-γ, TNF, and IL-5/IL-13 in total ILCs defined as Lin-IL7R+." (PMID 38567059, 2023).
acute respiratory distress syndrome (1 paper, 2016). Progressive and life-threatening pulmonary distress in the absence of an underlying pulmonary condition, usually following major trauma or surgery. "p38δ is also crucial in neutrophil chemotaxis pathway, contributing to acute respiratory distress syndrome (ARDS), and in mediating IL-13-driven mucus overproduction in human airway epithelial cells in chronic inflammatory lung diseases." (PMID 27148533, 2016).
aging (1 paper, 2020). A developmental process that is a deterioration and loss of function over time. "It further highlights that some poorly studied immune molecules should be considered in the context of cognitive aging, such as IL-13, here revealed as a new player in such interaction." (PMID 32983153, 2020).
AIDS (1 paper, 2019). A syndrome resulting from the acquired deficiency of cellular immunity caused by the human immunodeficiency virus (HIV). "On the other hand, the Th2-specific cytokines, i.e., IL-4, IL-5, IL-6, IL-10, and IL-13, are associated with disease progression and lead to the progression of HIV infection to AIDS." (PMID 31641392, 2019).
alopecia (1 paper, 2024). Hair loss usually from the scalp. "Recent clinical case studies indicate that blocking IL4 and IL13 during AD-associated alopecia can reverse the hair loss indicating that various JAK-STAT inducers can feed into the HFSC intrinsic cascade." (PMID 39521937, 2024).